PIWIL1 (piwi like RNA-mediated gene silencing 1)
Diseases named in the same sentence as PIWIL1 in open-access papers (continued):
Sharing a sentence is not in itself a finding about the gene and the disease.
lung adenocarcinoma (8 papers, 2015 to 2022). A carcinoma that arises from the lung and is characterized by the presence of malignant glandular epithelial cells. "Next, we evaluated the association between PIWIL1 expression and mutation status of known SMGs of lung adenocarcinoma." (PMID 29168346, 2018). "In this study, functional annotation of coexpressed genes based on TCGA lung adenocarcinoma data also indicated that overexpression of PIWIL1 was associated with embryonic development, cell proliferation, and regulation of transcription." (PMID 29168346, 2018). "High PIWIL1 expression was significantly associated with a shorter OS in lung adenocarcinoma patients (HR = 1.65, 95% CI = 1.28–2.13; P = 1.0 × 10 −4)." (PMID 29168346, 2018). "Using TCGA lung adenocarcinoma data, we further performed coexpression and Gene Ontology (GO) analyses, and analyzed the association of DNA methylation levels in PIWIL1 promoter region with its expression." (PMID 29168346, 2018). "Then, they examined the relationship between the PIWIL1 expression and mutations in lung adenocarcinoma, and eventually found that the PIWIL1 expression was remarkably higher in patients who did not have serine/threonine kinase 11 (STK11) or hepatocyte growth factor (HGF) mutations." (PMID 31890151, 2019). "In terms of PIWI protein, PIWIL1 expressed aberrantly in lung adenocarcinoma and NSCLC due to promoter DNA hypo-methylation and promotes proliferation, invasion and migration of cancer cells." (PMID 35637965, 2022). "We first evaluated the expression levels of PIWIL1 in TCGA lung adenocarcinoma and observed that PIWIL1 was overexpressed in tumors compared to normal tissues (P = 0.001)." (PMID 29168346, 2018). "PIWIL1 is an epidriver gene in lung adenocarcinoma, indicating a potential target for further therapy." (PMID 29168346, 2018). "Piwi‐like RNA‐mediated gene silencing 1 (PIWIL1) has been identified as a novel extremely highly expressed cancer‐testis (CT) gene in lung adenocarcinoma." (PMID 29168346, 2018). "Then, we used the Kaplan–Meier plotter tool to assess the relationship between the PIWIL1 mRNA expression and overall survival (OS) of lung adenocarcinoma patients using TCGA dataset." (PMID 29168346, 2018). "To characterize the PIWIL1 function in lung adenocarcinoma tumorigenesis and metastasis, we examined PIWIL1 expression in lung adenocarcinoma cells (A549 and H1299) by RT‐PCR and western blot analyses." (PMID 29168346, 2018). "Herein, we sought to investigate the role of PIWIL1 in the occurrence and development of lung adenocarcinoma." (PMID 29168346, 2018). "We examined the expression pattern of PIWIL1 in The Cancer Genome Atlas (TCGA) lung adenocarcinoma samples, and validated it by Real‐Time PCR (RT‐PCR) in additional 21 paired lung adenocarcinoma tissues and 16 normal tissues." (PMID 29168346, 2018). "Therefore, coexpression of PIWIL1 and TDGF1 might provide insights into the causal function of PIWIL1 in lung adenocarcinoma.There is growing evidence showing that activation of CT genes is an early event in tumorigenesis and mediated largely by the change in DNA methylation." (PMID 29168346, 2018). "In lung adenocarcinoma, PIWIL1 is considered to be a highly expressed CT gene." (PMID 33711953, 2021). "Our study first provided the evidence for the biological function of CT gene PIWIL1 in lung adenocarcinoma and demonstrated that activation of PIWIL1 expression in lung adenocarcinoma cells might facilitate cancer cell proliferation, invasion, and migration." (PMID 29168346, 2018). "According to this study, we found that PIWIL1 was overexpressed in lung adenocarcinoma (P < 0.001)." (PMID 29168346, 2018). "Overexpression of PIWIL1 could facilitate the proliferation, invasion and migration of lung adenocarcinoma cells and vice versa." (PMID 29168346, 2018). "Therefore, the specific expression characterizations of PIWIL1 confirmed that it was a CT gene in lung adenocarcinoma." (PMID 29168346, 2018).
lung adenocarcinoma (continued). "Importantly, we identified PIWIL1 as an epi‐driver gene in lung adenocarcinoma, suggesting its potential target for further therapy." (PMID 29168346, 2018). "Taking together, these observations suggested that PIWIL1 could promote the ability of proliferation, invasion and migration in lung adenocarcinoma." (PMID 29168346, 2018). "Therefore, we speculated that PIWIL1 may be an epi‐driver gene in lung adenocarcinoma.In conclusion, we identified that PIWIL1 was overexpressed in tumor tissues and associated with poor OS in lung adenocarcinoma patients." (PMID 29168346, 2018). "However, the exact function and mechanism of PIWIL1 in lung adenocarcinoma remains unclear." (PMID 29168346, 2018).
male infertility (7 papers, 2015 to 2024). The inability of the male to effect fertilization of an ovum after a specified period of unprotected intercourse. "Furthermore, an array-based DNA methylation profiling in male infertility established the role of allele-specific DNA hypermethylation of PIWIL1/2 involved in RNA-mediated gene silencing." (PMID 31484408, 2019). "Using WES on 2740 men with NOA or severe oligozoospermia, the IMIGC/GEMINI consortia demonstrated that pathogenic variants in the D-box region of PIWIL1 specifically, and variants elsewhere in the gene, are not a common cause of male infertility." (PMID 34498060, 2021). "PIWIL1 is known to exhibit the small RNA-guided RNase (slicer) activity, and the D633A single point mutation disrupts this ‘slicer’ activity, leading to LINE1 retrotransposon accumulation and male infertility." (PMID 26104391, 2015).
non-small cell lung carcinoma (7 papers, 2015 to 2024). A group of at least three distinct histological types of lung cancer, including non-small cell squamous cell carcinoma, adenocarcinoma, and large cell carcinoma. "Activation of the RASSF1C/MEK/ERK pathway has been shown to induce PIWIL1 expression in non-small cell lung cancer cells." (PMID 33718392, 2021). "It has been reported that downregulation of PIWIL1 and PIWIL2 by promoter CpG island hypermethylation has been observed in other types of tumors like testicular or non-small cell lung cancer." (PMID 32357464, 2020).
renal cell carcinoma (7 papers, 2019 to 2025). "However, a study in patients with renal cell carcinoma showed that high PIWIL1 expression is correlated with better prognosis." (PMID 33718392, 2021). "Downregulation of piRNA pathway genes in cancer may be uncommon but have been reported in testicular germ cell tumor (PIWIL1, PIWIL2, PIWIL4 and DDX4) and renal cell carcinoma (PIWIL1, PIWIL2 and PIWIL4) and now, also in our expression study for PIWIL2, PIWIL4 and TDRD1." (PMID 33374923, 2020). "Clinically, reduced expression of PIWIL4, along with PIWIL1 and PIWIL2, is correlated with unfavorable survival in renal cell carcinoma." (PMID 41208974, 2025). "However, real-time PCR analysis of renal cell carcinoma and non-tumor renal parenchyma tissues found a significant downregulation of PIWIL1 in renal cell carcinoma tissues." (PMID 33718392, 2021).
cervical cancer (6 papers, 2020 to 2024). A primary or metastatic malignant neoplasm involving the cervix. "In cervical cancer, PIWIL1 has been associated with enhanced sphere formation and tumorigenesis, increased resistance to cisplatin, and elevated expression of several stem cell self-renewal-genes (OCT4, NANOG and BMI1)." (PMID 33718392, 2021). "Ectopic PIWIL1 increased the chemical resistance of SiHa cervical cancer cells by regulating stem cell self-renewal-associated transcription factors." (PMID 35083142, 2021). "In cervical cancer cells, PIWIL1 overexpression leads to increased expression of stem cell markers POU5F1, NANOG and BMI1, while PIWIL1 downregulation has the opposite effect." (PMID 38303021, 2024). "Ectopic PIWIL1 overexpression in cervical cancer cells promotes tumor sphere formation by regulating the stem cell-related transcription factors OCT4, NANOG, KLF4, and BMI1, thus conferring resistance to cisplatin." (PMID 35083142, 2021). "After knocking down PIWIL1 in cervical cancer cells by shRNA, increased sensitivity to cisplatin was observed." (PMID 33718392, 2021). "We examined the RNA-seq data from the TCGA and found that there was also a positive correlation between PIWIL1 and ERα expression in cervical cancer, kidney cancer, prostate adenocarcinoma, testicular germ cell tumors and cutaneous melanoma (data not shown)." (PMID 32503542, 2020). "The study found that PIWIL1 could serve as a potential therapeutic target for inhibiting tumor growth and invasion in cervical cancer." (PMID 39596284, 2024). "PIWIL1 acts as a potential biomarker for predicting chemoresistance in cervical cancer." (PMID 38023199, 2023). "Also, a study of normal cervical tissues, high-grade squamous intraepithelial lesions (HSILs) and cervical cancer samples showed a significantly higher frequency of PIWIL1 protein expression in HSILs and cervical cancer tissues when compared with that in the normal cervical epithelium." (PMID 33718392, 2021). "A positive correlation between HPV16 E7 and PIWIL1 was detected in cervical cancer tissues, although the related mechanism has not yet been described." (PMID 33718392, 2021).
colon cancer (6 papers, 2010 to 2023). "In addition to miRNAs, lncRNA FALEC has been implicated in the regulation of PIWIL1 expression in colon cancer cells." (PMID 33718392, 2021). "This provided the initial evidence for eliminating the formation of functional piRNA/PIWIL1 complexes in a colon cancer cell line COLO205." (PMID 33718392, 2021). "For example, PLX4720 is a selective B-RAF inhibitor, and treatment with this drug strongly downregulates the expression of PIWIL1 in colon cancer cells." (PMID 33718392, 2021). "Overexpression of PIWIL1 is an early event in colon carcinogenesis, since it is significantly upregulated from the earliest stages (I and II) of colon cancer progression compared to normal colon tissues." (PMID 33718392, 2021). "To investigate the biological function of the PIWIL1–piRNA complex in colon cancer, we performed a target prediction analysis for 317 PIWIL1-bound piRNAs." (PMID 31694219, 2019). "In colon cancer cells, several piRNAs seem to be loaded into a complex consisting of PIWIL1 and specific mRNAs, indicating that the formation of PIWIL1/piRNA complex might exert biological roles in colon cancer." (PMID 33718392, 2021). "In addition, PIWIL1 overexpression with an adenovirus vector significantly increases the proliferation of colon cancer cells by increasing global DNA methylation levels." (PMID 33718392, 2021). "PIWIL1 promotes cancer growth and is associated with increased mortality; increased levels of PIWIL2 have been reported in breast and cervical cancer; and increased levels of PIWIL3 and PIWIL4 have been reported in colon cancer." (PMID 26373553, 2015). "This study demonstrated that depletion of FALEC by shRNA could significantly decrease the proliferation, migration, invasion, angiogenesis and tumorigenesis of colon cancer cells, whereas these inhibitory effects were largely counteracted by ectopic PIWIL1 overexpression." (PMID 33718392, 2021). "Of the EIF2C1-4 and PIWIL1-4 analyzed by logistic regression, we observed that an increased expression of EIF2C1 and PIWIL2 was significantly associated with occurrence of colon cancer tissue compared with non-cancer tissue." (PMID 20146808, 2010). "However, a similar study by Genzor and colleagues reports that PIWIL1 upregulation in colon cancer cells results in a lack of functional PIWIL1/piRNA complexes with no observable piRNA-independent functions of PIWIL1." (PMID 33803619, 2021).
esophageal cancer (6 papers, 2009 to 2022). A primary or metastatic malignant neoplasm involving the esophagus. "A higher amount of PIWIL1 protein expression in the cytoplasm of esophageal cancer cells is correlated to higher histological grade, advanced tumor stage, and poorer overall survival." (PMID 35155584, 2022).
ovarian carcinoma (6 papers, 2014 to 2026). A malignant neoplasm originating from the surface ovarian epithelium. "Previously, high expressions of MAGEA4 and PIWIL1 were found in epithelial ovarian cancer; furthermore, the expression of PRAME was found in ovarian, uterine, and other tumor types." (PMID 37835834, 2023). "Lim and colleagues showed that piRNA pathway genes are overexpressed in ovarian cancer and they proposed that PIWIL1 and MAEL inhibit cell invasion." (PMID 26373553, 2015). "In ovarian cancer we show for the first time that Piwil1 transcript may often be abnormal result in non functional product." (PMID 24932571, 2014). "Our integrated computational and clinical analyses indicate that the piR-823/PIWIL1/DNMT3B/CDH1 axis is a putative epigenetic regulator of EMT and cancer stemness in ovarian cancer." (PMID 41596471, 2026). "The heatmap revealed that PIWIL1, DNMT3B, OCT4, NANOG, and CDH2 were increased in most ovarian cancer samples, while CDH1 was downregulated, thus delineating clear expression differences between cancer and control samples." (PMID 41596471, 2026). "We examined the expression of piRNA pathway genes PIWIL1–4, MAEL and L1 in malignant EOC, benign tumors and normal ovary tissues, and also investigated possible roles of PIWIL1 and MAEL in ovarian cancer cell lines." (PMID 24932571, 2014). "PIWIL1 and MAEL were transiently over expressed in the ovarian cancer cell line SKOV3, followed by real-time measurements of cell invasiveness." (PMID 24932571, 2014). "In contrast to other cell systems, in vitro real-time invasion assay showed that over expression of piRNA pathway components such as PIWIL1 and MAEL has a repressive effect on ovarian cancer cell invasiveness." (PMID 24932571, 2014). "Furthermore, overexpression of PIWIL1 and MAEL suggests a role of these genes in reducing ovarian cancer cells invasiveness in vitro." (PMID 24932571, 2014). "In order to investigate the possible role of piRNA pathway genes in cancer progression, full-length PIWIL1 or MAEL transcripts were cloned and transfected transiently into the ovarian cancer cell line SKOV3 and assayed for invasiveness after 24 hrs of transfection." (PMID 24932571, 2014). "Expression of PIWIL1 and PIWIL2 has been found in a wide range of human cancers such as stomach, breast, gastrointestinal tract and endometrium and recently also in ovarian carcinoma." (PMID 24932571, 2014). "Since PIWIL1 and MAEL are up regulated in malignant EOC and expressed in the epithelial cells, we investigated if these two genes affect invasiveness of ovarian cancer cell lines that do not normally express these genes." (PMID 24932571, 2014).
sarcoma (6 papers, 2012 to 2021). A usually aggressive malignant neoplasm of the soft tissue or bone. "Using a mouse model, it was demonstrated that overexpression of PIWIL1 in sarcoma cells was sufficient to promote tumorigenesis, possibly through inducing global DNA methylation." (PMID 33718392, 2021). "Other studies describe how PIWIL1 downregulation in sarcoma inhibits cell growth and allows cell differentiation and support the idea that PIWIL1 tumorigenic activity is due to its ability to regulate DNA hypermethylation." (PMID 32357464, 2020). "PIWIL1 has recently been shown to inhibit differentiation of sarcoma precursors in vitro and to induce sarcomas in vivo." (PMID 25007054, 2014).
soft tissue sarcoma (6 papers, 2009 to 2021). A malignant neoplasm arising from muscle tissue, adipose tissue, blood vessels, fibrous tissue, or other supportive tissues excluding the bones. "Previous studies have demonstrated that Piwil1 played a key role in enhancing tumor malignant behavior including proliferation and invasion, as well as the potential importance of Piwil1 expression as a marker of poor prognosis in soft-tissue sarcoma and ductal adenocarcinoma of the pancreas." (PMID 26506848, 2015). "PIWIL1 protein over-expression has been detected in many tumor types (testicular seminomas, breast, endometrial, gastrointestinal, ovarian, prostate, and soft-tissue sarcoma), but not in normal tissue." (PMID 22591718, 2012).
glioblastoma (5 papers, 2019 to 2024). The most malignant astrocytic tumor (WHO grade IV). "As a CSCs marker, PIWIL1 has been found to promote the proliferation of glioblastoma CSCs and regulate their self-renewal and differentiation." (PMID 35083142, 2021). "Finally, PIWIL1 knockdown in glioblastoma decreased the expression of neural stem and progenitor cell markers OLIG2 and Nestin." (PMID 38303021, 2024). "As a result, PIWIL1 downregulation reduced the number of glioblastoma stem cells in the S phase." (PMID 38303021, 2024). "The role of PIWIL1 in apoptosis induction in glioblastoma is well known." (PMID 35083142, 2021). "Likewise, under disease conditions, namely in glioblastoma (GBM), PIWIL1 plays a significant role by promoting the self-renewal of glioma stem cells (GSCs)." (PMID 39717847, 2024). "Moreover, a study reported that PIWIL1 was expressed at higher levels in glioblastoma stem cells than in paired non-stem cells." (PMID 38303021, 2024).
infertile (5 papers, 2015 to 2025). "Piwil1 which binds and suppresses TE-derived piwi interfering RNAs (piRNAs) to maintain germline integrity and is associated with infertility of certain crosses in canids; it is thought to be a highly-conserved gene among amniotes." (PMID 40501859, 2025). "For example, PIWIL1 (piwi-like RNA-mediated gene silencing 1) plays a central role in spermatogenesis and was found to be differentially methylated in infertile patients, while lack of SYCP1 (synaptonemal complex protein 1) in otherwise healthy mice has been found to yield infertility." (PMID 26221191, 2015).
liver cancer (4 papers, 2012 to 2026). An epithelial or non-epithelial malignant neoplasm that arises from the liver. "As an oncogene, PIWIL1 has been reported to be overexpressed in several tumors, including endometrial, cervical, colon, ovarian, and hepatic cancer." (PMID 41596471, 2026). "It has been shown that PIWIL1 enhances energy production by regulating fatty acid metabolism and inhibits liver cancer progression." (PMID 36860864, 2023).
lymph node metastasis (4 papers, 2015 to 2024). "The results indicated that patients with high PIWIL1 expression tended to have a shorter survival, and additionally deeper tumor invasion, higher clinical stage, and more lymph node metastasis." (PMID 35003260, 2021). "The results convincingly confirmed the present main viewpoint that overexpression of PIWIL1 was associated with the OS, CSS, DFS/RFS, tumor invasion, clinical stage, and lymph node metastasis." (PMID 35003260, 2021). "However, PIWIL1 positive expression was significantly associated with deeper tumor invasion (n = 5, OR = 2.26, 95% CI: 1.09–4.70, p=0.03), higher clinical stage (n = 6, OR = 1.53, 95% CI: 1.09–2.14, p=0.01), and more lymph node metastasis (n = 4, OR = 1.90, 95% CI: 1.25–2.88, p=0.003)." (PMID 35003260, 2021). "The expression of Piwil1, Piwil2, Piwil13, and Piwil4 were positively correlated with T stage, lymph node metastasis and clinical TNM and patients with higher expression had shorter survival time." (PMID 26506848, 2015). "These analyses showed that increased Piwil1 expression was significantly associated with FIGO stage (P = 0.042), lymphovascular space involvement (P = 0.000), lymph node metastasis (P = 0.026), and level of myometrial invasion (P = 0.048), but not with patient age or histological grade." (PMID 26506848, 2015). "We found that Piwil1 expression was significantly correlated with FIGO stage, lymphovascular space involvement, lymph node metastasis and level of myometrial invasion." (PMID 26506848, 2015). "However, when patients were stratified, PIWIL1 was an independent negative prognostic indicator in patients without lymph node metastases." (PMID 38303021, 2024).